EGFR (epidermal growth factor receptor)
Diseases named in the same sentence as EGFR in open-access papers (continued):
Sharing a sentence is not in itself a finding about the gene and the disease.
glioma (continued). "First, we confirmed that alisertib treatment increased B7-H3, SDCBP, and phosphorylated EGFR expression in glioma cells." (PMID 39928563, 2025). "In gliomas with EGFR mut/amp, growth factor signaling can directly promote amino acid uptake and utilization through increased Akt activity and mTORC1 activation." (PMID 40786409, 2025). "At the same time, the combination of circRNAs with epidermal growth factor receptor (EGFR) or histone deacetylase (HDAC) inhibitors has shown significant potential in restoring drug sensitivity in resistant glioma cells." (PMID 40723354, 2025). "Constitutive JNK activation has been reported in gliomas and correlates with histological grade and epidermal growth factor receptor (EGFR) expression in diffuse gliomas." (PMID 41226237, 2025). "EGFR, FAT4, and BCOR were the three features associated with 64% ACC using the TCGA glioma grading set." (PMID 40362575, 2025). "DET also affects glioma cell death by inhibiting the expression of EGFR/JUN (DET's core targets) and the core components of PI3K/AKT pathway." (PMID 39850823, 2024). "Rindopepimut (also known as CDX-110), a vaccine targeting the epidermal growth factor receptor (EGFR) deletion mutation EGFRvIII, has received drug approval from the US FDA for the breakthrough treatment of EGFRvIII-positive gliomas in adult patients." (PMID 39175478, 2024). "Most causal genes underwent copy number variation (CNV) in glioma samples, with AS3MT, DNA2, and SCDF1 being predominantly heterozygous deletion, while RASA4 and EGFR were predominantly heterozygous and homozygous amplification." (PMID 39722126, 2024). "It seems to be an interesting direction for future work to test the effect of ALA-PDT on the EGFR expression by glioma cells as testing other cancer cells has demonstrated the potential to lead to a reduction in the EGFR levels." (PMID 39201395, 2024). "Recently, it was reported that activation of EGFR in glioma results in elevated glucose uptake and lactate production, and the PKM2 levels correlated with levels of EGFR activity in GBM." (PMID 38514913, 2024). "Radiomics models have been developed to predict genetic features like MGMT methylation and EGFR-A289V mutations in high-grade gliomas and ATRX mutations in lower-grade gliomas (LGGs)." (PMID 38927583, 2024). "The first indication in support for the anti-tumor effect of cannabinoids in glioma emerged from studies describing epidermal growth factor receptors (EGFR) ligand amphiregulin increases the resistance to Δ9-THC antitumor effect in glioma xenograft." (PMID 39796008, 2024). "Logistic regression analysis further confirmed SIRPB1's significant association with WHO grade, IDH status, 1p/19q co-deletion, primary therapy outcome, and EGFR status in glioma samples." (PMID 38594692, 2024). "In HT-29 human colon adenocarcinoma cells, primary human colon cancer cells, A172 human glioma cell line and primary human glioma cells, Ninjurin 2 forms a complex with EGFR." (PMID 39594667, 2024). "Epidermal growth factor receptor (EGFR) found to be involved in non‐small lung cancer having connected pathways with prostate cancer, melanoma, glioma, bladder cancer and endometrial cancer." (PMID 39434198, 2024).
glioma (continued). "A comprehensive understanding of cancer genomics and tumor immunology would reveal disease mechanisms and elucidate the limited success of targeted therapies such as epidermal growth factor receptor (EGFR) inhibition in glioma." (PMID 38515213, 2024). "MDIG is an oxygen-sensitive protein that promotes angiogenesis and glioma growth by activating the EGFR/p-EGFR/VEGFA/VEGFR1/R2 pathway." (PMID 38687357, 2024). "A circular RNA-encoded oncogenic E-cadherin variant is essential for the maintenance of the oncogenicity for glioma stem cells by activating EGFR independently of EGF via binding to the EGFR CR2 domain." (PMID 38075205, 2024). "In the in vivo study, tumor volume in the mice implanted with EGFRvIII+ and IL-13Rα2+ glioma cells increased significantly in comparison with the mice implanted with WT epidermal growth factor receptor (EGFR) glioma cells." (PMID 38339374, 2024). "Another protein called melanoma differentiation associated gene-9/syntenin (MDA9) has been shown to maintain protective autophagy in glioma stem cells through EGFR signaling and phosphorylation of BCL2." (PMID 39062119, 2024). "The usage of Slrig1, a negative regulator of the oncogenic epidermal growth factor receptor (EGFR) family, disrupted downstream signalling in both wild-type and constitutively active EGFR mutated glioma cells (EGFRvIII) in vitro and in vivo." (PMID 39120301, 2024). "Due to the recurrence and resistance of gliomas, single-target inhibitors of EGFR or PI3K/AKT often fail." (PMID 39850823, 2024). "One noteworthy EGFR mutation, known as EGFR variant III (EGFRvIII), has been observed in 30% to 50% of gliomas with increased EGFR expression." (PMID 38686058, 2024). "The data on the direct effect of PDT on the EGFR expression by glioma cells are inconclusive and disparate." (PMID 39201395, 2024). "In Grade 4 gliomas (n = 75), 61 patients (81.3%) had IDH1 mutations and 1 patient (1.3%) had an EGFR-amp." (PMID 38893240, 2024). "The issue of drug resistance in gliomas is currently being tackled through multi-targeted therapies, including those aimed at the epidermal growth factor receptor (EGFR) and its downstream signaling pathways, such as PI3K." (PMID 39850823, 2024). "Recent research suggests that mutations and overexpression of EGFR in both pediatric and adult low-grade gliomas (G2) can lead to the activation of the RAS/MAPK kinase pathway, driving the proliferation of glioma cells." (PMID 38254732, 2024). "On the other side, IDH wildtype gliomas include astrocytomas, IDH wildtype, grade 2 and 3, and GBM (expressing TERT or EGFR mutations, or gain of chromosome 7 and loss of chromosome 10)." (PMID 39055532, 2024). "In this case, RevTM is involved in the recognition of the GD2 or EGFR antigen located on glioma cells and the target epitope of RevCAR-T cells." (PMID 38339374, 2024). "We reviewed glioma patients between 2011 and 2022 at our hospital, and included 187 adult glioma patients with available tumor tissue for detection of EGFR Amp and other 59 molecular markers of interest." (PMID 38595969, 2024). "Most causal genes underwent CNV in glioma samples, with AS3MT, DNA2, and SCDF1 being predominantly heterozygous deletion, while RASA4 and EGFR were predominantly heterozygous and homozygous amplification." (PMID 39722126, 2024). "Our genomic microarray data and validation results, showing higher EGFR mRNA as well as MAP2K mRNA levels in G2 glioma grade compared to G3 and G4 grade, provide new information regarding the genetic status of low-grade glioma in adults." (PMID 38254732, 2024).
glioma (continued). "Another factor known to stimulate both cell proliferation and migration is the epidermal growth factor (EGF); the overexpression of its receptor (EGFR) characterizes, indeed, high-grade gliomas." (PMID 39194524, 2024). "High EGFR levels contribute to glioma development, progression, and resistance in both kinase-dependent and -independent ways." (PMID 39201395, 2024). "Several well-characterized oncogenic pathways have recently been shown to regulate CD47 expression in GBM cells and glioma stem cells (GSCs) including Epidermal Growth Factor Receptor (EGFR) beta catenin." (PMID 39194679, 2024). "EGFR Amp leads to overexpression of EGFR protein in glioma cells, contributing to tumor proliferation, angiogenesis and invasion via RAS and PI3K/AKT signaling pathway." (PMID 38595969, 2024). "Specifically, the overexpression of YTHDF2 in glioma is due to the activation of EGFR/SRC/ERK pathway." (PMID 38398118, 2024). "Although EGFRvIII demonstrates promising targeting capability and therapeutic potential in gliomas, the widespread expression of EGFR and its crucial role in tumorigenesis render it an equally significant target antigen." (PMID 39506843, 2024). "Eight days later, tumor regression was also observed in mice implanted with EGFR-expressing gliomas." (PMID 38339374, 2024). "It has been reported that IFI30 can promote the EMT process in glioma cells by activating EGFR/AKT/GSK3β/β-catenin." (PMID 38517387, 2024). "Current prognostic tools for glioma primarily rely on factors such as WHO grade, IDH mutations, 1p/19q codeletion, MGMT promoter methylation, TERT promoter mutations and EGFR amplification." (PMID 39355251, 2024). "Following the great clinical success in other cancers, experimental targeting of EGFR in gliomas has also been intensively studied in both preclinical and clinical settings, as explained later." (PMID 39062807, 2024). "EGFR signaling through extracellular signal-regulated kinases 1/2 and casein kinase-2 in glioma cells leads to the phosphorylation of α-catenin and promotes β-catenin transactivation, which is associated with a high grade of glioma malignancy." (PMID 38473403, 2024). "Soluble proteins were purified by IMAC followed by SEC, concentrated and buffer exchanged into PBS prior to testing in vitro activity in an EGFR-expressing glioma line, CT2A-EGFRviii." (PMID 38697982, 2024). "We demonstrated that up to eight infusions of 10 × 109 EGFR BATs were feasible, safe, and well tolerated in both every 4-week and weekly regimens while inducing cellular and cytokine/chemokine anti-glioma immune responses." (PMID 38263486, 2024). "Other molecules, including stromal-derived factor 1 (SDF-1), granulocyte monocyte-colony stimulating factor (GM-CSF), and epidermal growth factor receptor (EGFR) are secreted by microglia to facilitate glioma invasion." (PMID 38473812, 2024). "Clinical, radiological and pathological data was analyzed based on the status of EGFR Amp in different glioma subtypes." (PMID 38595969, 2024). "HDAC6 promotes glioma cell proliferation and confers TMZ resistance to glioma cells, mainly by stabilizing and activating EGFR." (PMID 39057168, 2024). "The insulin receptor, expressed at the BBB and on glioma cell membranes, along with the epidermal growth factor receptor (EGFR) found in brain tumor cells, are key targets for brain delivery via immuno-liposomes." (PMID 39204177, 2024). "Our findings show that DET inhibits glioma invasion and proliferation by downregulating EGFR, JUN, and PI3K/AKT." (PMID 39850823, 2024). "On the contrary, in IDH-mutant gliomas, EGFR alterations were less common and its prognostic value was under evaluated." (PMID 38595969, 2024).
glioma (continued). "It has been proven that the expression of Fyn in glioma patients is closely related to EGFR, and Fyn is a direct effector molecule of carcinogenic EGFR and significantly promotes the invasion of glioma cells with high expression of EGFR22." (PMID 38714727, 2024). "Further, abnormal EGFR-mTOR signaling was recently reported to be involved in the malignant transformation of IDH-mutant gliomas through the upregulation of c-Myc." (PMID 38481314, 2024). "EGFR amplification and overexpression and PTEN mutation or loss are important factors leading to the progression of glioma." (PMID 38348047, 2024). "SRY-box transcription factor 2 (SOX2), epidermal growth factor receptor (EGFR), and Myc proto-oncogene (MYC) are genes whose upregulation is associated with glioma stemness." (PMID 39419964, 2024). "The development of glioma vaccines aims to target tumor-specific antigens similar to those recognized by Chimeric Antigen Receptor T (CAR-T) cells, such as EGFR variant III (EGFRvIII) and Interleukin-13 Receptor Alpha 2 (IL-13Rα2)." (PMID 38534769, 2024). "CBX3 has been suggested to increase glioma growth by repressing transcription of E3 ubiquitin ligases that target epidermal growth factor receptor (EGFR)." (PMID 39545414, 2024). "Several studies have also indicated the use of inhibitors for the epidermal growth factor receptor (EGFR) due to the strong involvement of the downstream PI3K/Akt pathway in glioma cell proliferation." (PMID 38666818, 2024). "This shows the potential neuroprotective effect of progesterone against glioma due to its influence on EGFR expression and other signaling pathways." (PMID 38666818, 2024). "The regulatory factors that have been found to be associated with glioma include Phosphatase and Tensin Homolog (PTEN), Epidermal growth factor receptor (EGFR), ATG family, Beclin1, and Mammalian target of rapamycin (mTOR)." (PMID 38304870, 2024). "Specifically, EGFR RNA expression and copy number amplification were highly concordant, suggesting that genetic control is dominant for EGFR expression in gliomas." (PMID 38363490, 2024). "By exploiting the molecular alterations specific to gliomas, such as mutations in the IDH gene and amplification of the EGFR gene, targeted therapies aim to selectively disrupt pathways crucial for tumor growth and survival." (PMID 38801243, 2024). "Amplifications in the EGFR gene are detected in 57.4% of primary GBM patients, leading to high levels of EGFR protein and it has been observed that amplifications of the EGFR are retained in recurrent gliomas." (PMID 39766391, 2024). "Next, the authors tested the ability of CAR-T M27-28BBZ cells to inhibit the growth of glioma cells expressing EGFRvIII, EGFR or both antigens in orthotopic GBM xenografts models." (PMID 38339374, 2024). "EGFR VIII is a unique mutant subtype of EGFR in gliomas, and the CRISPR-Cas13a system can induce the death of glioma cells overexpressing EGFR VIII." (PMID 38524179, 2024). "EGFR Amp has been established as an independent marker for poor overall survival (OS) in IDH-wildtype lower grade gliomas, which was close to that of GBM." (PMID 38595969, 2024). "Among the Grade 2 gliomas (n = 26), 17 cases (65.3%) exhibited IDH1 mutations, while 3 patients (11.5%) had EGFR-amp." (PMID 38893240, 2024).
glioma (continued). "Since IFN-γ can both inhibit the malignant phenotype of glioma cells and maintain the killing activity of immune cells, and EGFR serves as an important factor in glioma progression, it is necessary to explore the effect of IFN-γ on EGFR in gliomas." (PMID 37759950, 2023). "The same subunit was reported as a substrate for EGFR in glioma cells, where EGFR phosphorylates the COOH-terminal domain of the subunit, leading to an increase in glutamate-NMDAR signaling." (PMID 38004424, 2023). "Within the framework that EGFR genomic alterations showed significant cis-effect on its cognate protein, there are several scenarios by which EGFR impacted the clinical outcomes of glioma." (PMID 36720864, 2023). "Spatially-resolved models of some genomic aberrations in gliomas (e.g. copy number variations in EGFR, PDGFR, etc.)have already been developed, with accuracies ranging from 37.5% to 87.% depending on the gene of interest." (PMID 37849813, 2023). "MET is among the top three dysregulated receptor tyrosine kinases (RTKs) in glioma cells, along with EGFR and PDGFRA." (PMID 37214395, 2023). "Glioma is the most common central nervous system (CNS) malignancy and presents frequent alterations that activate epidermal growth factor receptor (EGFR) and PI3K pathways." (PMID 37877351, 2023). "More recently, it was reported that OLIG2 modulates growth factor signaling in two distinct populations of glioma stem-like cells depending on their EGFR or PDGFRα expression." (PMID 37511403, 2023). "Another example of boronated PAMAM dendrimer was functionalized with the epidermal growth factor (EGF), since the EGFR gene is found on the cell surface of the majority of high-grade gliomas." (PMID 37631334, 2023). "The SHOX2high group (n = 175) showed high frequency of somatic mutations in the EGFR (40%), PTEN (36%), TTN (36%) and MUC16 (26%) genes in glioma." (PMID 37170390, 2023). "By introducing dual-specific CAR-NK cells expressing cetuximab-based CAR (cetuximab: EGFR inhibitor), lysis of both EGFRvIII and wildtype EGFR expressing glioma cells in vivo was observed in a GBM mouse model." (PMID 37046685, 2023). "Given the important role of EGFR amplification in glioma progression, EGFR amplification has been incorporated as one of the criteria for molecular classification of GBM in the WHO CNS5 classification." (PMID 37759950, 2023). "The combination of sulfasalazine and MK-801 also showed antiproliferative properties in EGFR-overexpressing glioma cells." (PMID 36619229, 2023). "This was also reflected by the strong positivity of EGFR in glioma cells when compared to weak immunoreactivity of glioses documented previously." (PMID 37568909, 2023). "After excluding IDH1 R132H mutant gliomas from the analysis, the specificity increased to 41.5% for EGFR, 53.2% for MEOX2, 50.7% for SOX11 and 57.3% for INSM1." (PMID 37568909, 2023). "The amino derivative compound 17 has the strongest effect against EGFR and glioma cells U251, T98G, and U87." (PMID 37570648, 2023). "Through our current research, we provide the promising possibility of a combination of immunotherapy and EGFR-targeted medicine in gliomas." (PMID 37759950, 2023). "Signaling pathways, including the MAPK, PI3K, focal adhesion‐PI3K/AKT/mTOR, and EGFR pathways, were enriched in gliomas with high MAPK4 expression." (PMID 36999945, 2023). "The EGFR gene amplification is common in all gliomas, accounting for 40 to 50 percent of primary GBMs." (PMID 37762559, 2023). "EGFR signalling promotes glioma cell survival, proliferation, and migration by an activation of PI3K/Akt or MAPK signalling pathways." (PMID 37568909, 2023). "Furthermore, our findings emphasized EGFR mutational status may be relevant for the further conduct and planning of clinical trials investigating the therapeutic value of immune modulatory treatment strategies in glioma patients." (PMID 36720864, 2023).